STAT1 (signal transducer and activator of transcription 1)
Diseases named in the same sentence as STAT1 in open-access papers (continued):
Sharing a sentence is not in itself a finding about the gene and the disease.
kidney (11 papers, 2017 to 2025). "Collectively, our studies demonstrate that HDAC9 contributes to G2/M arrest in tubular epithelial cells by regulating the activation of STAT1, followed by promoting production of profibrotic cytokine, finally causing kidney tubulointerstitial fibrosis." (PMID 37230975, 2023). "Here we found that these lung tumor infiltrating macrophages (CD11b+ F4/80+ gated on CD3−) strongly expressed PD-L1 in tumor bearing STAT1 KO mice compared to tumor bearing Bl6/C67j mice." (PMID 30647851, 2018). "We investigated MWCNT-induced lung inflammation, allergic airway remodeling and fibrosis in Stat1+/+ or Stat1−/− mice in vivo for one and 21 days after oropharyngeal aspiration of tMWCNTs or rMWCNTs." (PMID 28716119, 2017). "In addition, STAT1 inhibition decreased the expression of pro‐inflammatory and pro‐fibrotic cytokines in the kidney lesion area." (PMID 33448153, 2021). "Although impaired STAT1 activation appears to occur predominantly in Casp11−/− IECs during colorectal tumorigenesis, we sought to determine whether caspase-11 also has the ability to regulate STAT1 activity in primary macrophages." (PMID 30538296, 2019). "Since we demonstrated that CNF1 impacts macrophage polarization through NF-κB and JAK-STAT1 signaling pathways, we evaluated the effect of NF-κB or STAT1 inhibitor on CNF1-induced M1 macrophage polarization and kidney injury in vivo." (PMID 35766380, 2022).
adenocarcinoma (9 papers, 2012 to 2024). A common cancer characterized by the presence of malignant glandular cells. "RNA levels of both Oct4 and Stat1 increased 1.2- and 1.6-fold, respectively, in the lungs of adenocarcinoma patients compared with the controls." (PMID 34685622, 2021). "The level of IRF1 was correlated with that of STAT1 in the normal tissue of adenocarcinoma." (PMID 30305853, 2018).
neurological disease (9 papers, 2013 to 2025). "To examine whether the observed effects of IFN‐γ and its dependence on STAT1 might help explain the associations between microglial priming and neurological disorders, we evaluated the behavior of the mice treated as described in Section 3.4 using a battery of tests." (PMID 39392762, 2024). "Cytokines and oxidative stress are known to induce aberrant STAT1 activation in several neurological disorders, contributing to inflammation and neuronal damage." (PMID 41462595, 2025). "Stat1 phosphorylation is triggered by type 1 and 2 interferons, leading to activation of interferon-related gene expression, which are important in antiviral immune responses, as well as in neurological diseases." (PMID 38936775, 2024). "Since GLS1 converts glutamine into glutamate, which is neurotoxic when in excess levels, GLS1 regulation through STAT1 may have an adverse effect in the CNS that are relevant to various neurological diseases." (PMID 24086752, 2013). "Although neurological disease for MACV has been described in guinea pigs, neurological manifestations are less common than those exhibited in our STAT-1 model." (PMID 40733611, 2025). "TBI-induced protein upregulation (MUG-1, PZP, GFAP, TJP, STAT-1, and CD44) across hippocampal sub-regions indicates shared molecular responses and links to neurological disorders." (PMID 38735925, 2024). "The study shows that proteins (SOX2, STAT1, AKT1, and CTNNB1) can be used as markers for neurological disease at the early stage of neuronal development, and they can be potential drug targets for therapeutic development." (PMID 30598663, 2018). "Although a STAT-1−/− mouse model of MACV disease has been described previously, this model resulted in lethality by 8 days post challenge with a lack of neurological disease manifestations." (PMID 40733611, 2025).
hematological malignancies (8 papers, 2018 to 2025). "Fluda is a fluorinated purine nucleoside analog that is used in various hematological malignancies, and it is a STAT1 inhibitor." (PMID 40336064, 2025). "In terms of translating these results into metabolism-targeted therapies, evidence suggests that fludarabine, commonly used for hematological malignancies, inhibits STAT1 activity." (PMID 39518046, 2024). "This is consistent with prior studies showing CCRL2’s interaction with TLR4 in macrophages, enhancing its stability and supporting NF-κB activation, and its involvement in IFN-γ/STAT1 signaling in hematologic malignancies, even in the absence of exogenous cytokine." (PMID 40867595, 2025).
neurodegenerative disease (8 papers, 2012 to 2025). A disorder of the central nervous system characterized by gradual and progressive loss of neural tissue and neurologic function. "Among the immune-related protein interactors of Kv1.3 that were measured by our MS studies, we nominated C3 and STAT1 as proteins of interest to be validated by Luminex based on their known role in several neuroinflammatory and neurodegenerative diseases." (PMID 38936775, 2024). "Inhibiting the IFN‐γ/STAT1 axis may be a way to treat neurodegenerative diseases and psychiatric disorders that involve microglial priming." (PMID 39392762, 2024). "Targeting IFN‐γ and/or STAT1 may be a strategy to treat neurodegenerative diseases and psychiatric disorders that involve microglial hyperactivity." (PMID 39392762, 2024). "In addition to STAT1 and type I IFNs, dysregulated glutaminase has also been indicated in a few animal models of neurodegenerative diseases." (PMID 22479354, 2012). "Because both type I IFN and STAT1 are elevated in HAD and many other neurodegenerative diseases, our study may help to identify novel mechanisms as well as therapeutic interventions toward those diseases." (PMID 24086752, 2013). "Thus, the down-regulation of STAT1, STAT2, IRF7 and IRF9 through GSK-J4 could inhibit neurodegenerative diseases as well as brain inflammation." (PMID 28747667, 2017). "However, the role of STAT1-mediated gene regulation has not been previously implied in inherited neurodegenerative diseases." (PMID 28774347, 2017).
kidney disease (7 papers, 2012 to 2025). "Given our observation that STAT1, STAT3 and NFκB contribute to the aging transcriptional program, we used the genes for these transcription factors as candidates to find out if they are associated with either kidney function or renal disease susceptibility." (PMID 26678048, 2015). "Therefore, the results from the renal disease models suggest that elevated activity of STAT1, STAT3 and NFκB may have a deleterious effect on kidney physiology and function in old age." (PMID 26678048, 2015). "Though CXCL10 and EGF have been reported altered in a variety of renal diseases, even in the kidney rejection, the network of CXCL10, EGF and STAT1 in BKVN has not been reported." (PMID 29567951, 2018).
respiratory diseases (6 papers, 2022 to 2025). "By reducing STAT1 nuclear translocation, RSV creates an optimal environment for RSV to infect and replicate in epithelial cells, thereby causing respiratory disease." (PMID 38938568, 2024).
endocrinopathy (5 papers, 2019 to 2025). "Other genetic defects that lead to endocrinopathies include loss-of-function changes in IL2RA, STAT5B and GOF in STAT3 and STAT1." (PMID 40704637, 2025). "In the largest cohort of patients with STAT1 GOF, autoimmune diagnoses were present in 37% of patients, with endocrinopathy being the most common manifestation." (PMID 40704637, 2025).
metabolic disorders (4 papers, 2010 to 2024). "These pathways activate multiple signals including EIK-1, c-Jun, ATF-2, c-Fos, Myc, and STAT1 which involve in cell migration and invasion, cellular proliferation, cell survival, and metabolic disorders." (PMID 39149564, 2024).
blood cancers (3 papers, 2008 to 2022). "It has also been observed to decrease the proliferation and survival of cell lines derived from hematological neoplasms by decreasing the expression of crucial transcription factors such as NK-κB, STAT1, or MYC." (PMID 34975915, 2021). "In blood cancers, however, STAT1, STAT3 and STAT5 play a dominant role and single STAT‐targeting therapies may suffice, also reflecting their less complex genetic driver mutation landscape." (PMID 35229974, 2022).
gastrointestinal tumor (3 papers, 2023 to 2025). "In this context, we provide a comprehensive overview of the downstream factors associated with the IFN-γ/STAT1 pathway in gastrointestinal tumors." (PMID 40909948, 2025). "In this review, we systematically organized the downstream factors of the IFN-γ/STAT1 pathway that promote or inhibit gastrointestinal tumors." (PMID 40909948, 2025). "The following section summarizes the inhibitory effects exerted by the IFN-γ/STAT1 pathway on the progression of gastrointestinal tumors." (PMID 40909948, 2025). "The expression and function of STAT1 greatly influence gene expression, playing a crucial role in the pathogenesis and progression of gastrointestinal tumors." (PMID 40909948, 2025). "The preceding section provided a detailed examination of the role of the IFN-γ/STAT1 pathway in promoting gastrointestinal tumors." (PMID 40909948, 2025). "This phenomenon consequently strengthens the antitumor immunity via the IFN-γ/STAT1 pathway in gastrointestinal tumors." (PMID 40909948, 2025). "In this review, we summarize the functions, mechanisms, and key factors of the IFN-γ/STAT1 pathway that promote or inhibit gastrointestinal tumor progression and discuss therapeutic prospects for targets of the pathway." (PMID 40909948, 2025). "The current research on gastrointestinal tumors has further validated the critical role of the IFN-γ/STAT1/JAK/CXCL chemokine pathway—particularly involving CXCL9 and CXCL10—in promoting antitumor immune responses." (PMID 40909948, 2025). "In this review, we summarized the research regarding the activation of the IFN-γ/STAT1 pathway in gastrointestinal tumors." (PMID 40909948, 2025). "The IFN-γ/STAT1 pathway plays a dual role in promoting and inhibiting gastrointestinal tumors." (PMID 40909948, 2025). "This regulatory interplay suggests that the IFN-γ/STAT1 pathway may confer a protective mechanism against apoptosis resistance in gastrointestinal tumors by diminishing survivin expression." (PMID 40909948, 2025). "Therefore, it is essential to closely examine the functional similarities and heterogeneity of the IFN-γ/STAT1 pathway in gastrointestinal tumors when developing targeted therapeutic options focused on relevant downstream factors." (PMID 40909948, 2025). "In the previous section, we have substantially introduced the potential therapeutic targets of the IFN-γ/STAT1 pathway in gastrointestinal tumors, as well as the molecules and medicines that may have therapeutic effects against different targets." (PMID 40909948, 2025). "The fact that molecules or medicines affect STAT1 phosphorylation in different ways within different digestive organs may explain the differences in clinical benefit of treating different gastrointestinal tumors with the same molecule or drug." (PMID 40909948, 2025). "Furthermore, modulating STAT1 activity with various molecules or medicines may offer additional therapeutic benefits in gastrointestinal tumor treatment." (PMID 40909948, 2025). "Recent research has expanded our understanding of the role of NKA beyond the nervous system, particularly in gastrointestinal tumors, where it appears to have a significant function related to the IFN-γ/STAT1 pathway." (PMID 40909948, 2025). "In summary, IRF-1 plays a multifaceted role in the progression of gastrointestinal tumors, primarily through the IFN-γ/STAT1 pathway." (PMID 40909948, 2025). "We further found NOTCH3 levels in gastrointestinal tumor to correlate with markers of Dendritic cell(HLA-DPB1, HLA-DRA, HLA-DPA1, BDCA-4), Tfh(T-bet, STAT4, STAT1, TNF-α), Treg cells (FOXP3, CCR8, STAT5B, TGFβ) and T cell exhaustion (PD-1, CTLA4, LAG3, TIM-3)." (PMID 38906903, 2024). "Here, we found that molecules or medicines focused on affecting the phosphorylation of STAT1 in the pathway to control the progression of gastrointestinal tumors more often than not." (PMID 40909948, 2025).
gastrointestinal tumor (continued). "In addition, we also searched clinical treatment trials for gastrointestinal tumors related to the IFN-γ/STAT1 pathway, although the search results were not what we expected." (PMID 40909948, 2025).
head and neck tumor (3 papers, 2008 to 2025). "But, STAT1 expression is lower in head and neck tumor than normal tissue." (PMID 26993600, 2016).
intestinal disease (3 papers, 2019 to 2022). "We show that caspase-11 is required for IL-1β- and LPS-driven STAT1 activation in IECs, suggesting that caspase-11 facilitates crosstalk between MyD88 and STAT1 signalling pathways at the intestinal barrier, to promote anti-tumorigenic signalling during inflammation-associated intestinal disease." (PMID 30538296, 2019).
myopathy (3 papers, 2017 to 2022). A disease of the muscle in which the muscle fibers do not function properly. "JAK/STAT1 inhibitors fully prevented IFN-γ-induced myopathy as well, confirming the critical role of STAT1 activation in the proinflammatory action of IFN-γ." (PMID 35406795, 2022). "Type I interferon is also involved in myopathy in patients with DM through the STAT1 signaling pathway." (PMID 34580642, 2021). "Moreover, type I interferon can participate in the myopathy of patients with DM through the STAT1 signaling pathway, resulting in muscle tissue damage." (PMID 34580642, 2021). "Concurrently, PGC1β up-regulates apoptosis and/or autophagy transcriptional factors such as E2f1, Atf3, Stat1, and Stat3, which may be facilitating myopathy." (PMID 28860475, 2017).
psychiatric disorder (3 papers, 2017 to 2024). A disorder characterized by behavioral and/or psychological abnormalities, often accompanied by physical symptoms. "This study establishes the “AU020206-IRFs-STAT1-cytokine axis” involved in the abnormal immunity in the brain of MIA female offspring, which serves as a potential therapeutic target of psychiatric disorders induced by MIA." (PMID 39310110, 2024). "We also identified specific TFBSs enriched in psychiatric disorder meQTL targets such as TAF1 and STAT1." (PMID 29066808, 2017).
colonic (2 papers, 2023 to 2025). "CDK1 and STAT1 may serve as early diagnostic indicators for kidney injury in patients with digestive system cancers." (PMID 39911265, 2025).
genetic disorders (2 papers, 2021 to 2023). "In fact, mutations in STAT1 and STAT3 that dissociate latent dimers give rise to rare genetic disorders of the immune system." (PMID 37059181, 2023).
benign tumor (1 paper, 2018). "We compared the expression of STAT1 and its phosphorylated forms (pSTAT1-Y701 and pSTAT1-S727) in normal ovarian tissues and tissues of benign tumor, serous borderline tumor, and high-grade serous malignant carcinoma via immunohistochemistry." (PMID 29751820, 2018).
retinopathy (1 paper, 2016). "Taken together with these reports, our findings support a role for EP300 as a key modulator of the anti-apoptotic effects of the endogenously activated STAT1/3–IL6ST/OSMR axis in light-induced retinopathy." (PMID 27242532, 2016). "Collectively, these findings are consistent with the possibility that STAT1/3–IL6ST/OSMR axis may be activated in light-induced retinopathy as an endogenous anti-apoptotic signaling pathway." (PMID 27242532, 2016). "Therefore, the retinopathy-associated increase in IL6ST and OSMR detected here may be a result of STAT1/3-mediated transcriptional activation." (PMID 27242532, 2016).
skeletal dysplasia (1 paper, 2008). Any Mendelian diseases that affects growth and development of the skeleton. "Here, we analyzed STAT1 activation by the N540K, G380R, R248C, Y373C, K650M and K650E-FGFR3 mutants associated with skeletal dysplasias." (PMID 19088846, 2008). "To answer this question, we compared six FGFR3 mutants, which together account for the majority of the known skeletal dysplasia cases, for their activation of STAT1 and ERK MAP kinase, and their effects on chondrocyte growth." (PMID 19088846, 2008). "The majority of evidence supporting the role of STAT1 in FGFR3 signaling in cartilage was obtained using the K650M or K650E mutants, which account for only a small subset of FGFR3-related skeletal dysplasia cases." (PMID 19088846, 2008). "Thus the ability to activate STAT1 appears restricted to the K650M and K650E-FGFR3 mutants, which however account for only a small minority of the FGFR3-related skeletal dysplasia cases." (PMID 19088846, 2008).
STAT1 also shares sentences with these, for which no sentence is quoted: viral diseases (12 papers); candidiasis (10); oral squamous cell carcinoma (9); combined immunodeficiency (5); graft versus host disease (5); hemophagocytic lymphohistiocytosis (5); leishmaniasis (5); anaplastic large cell lymphoma (4); DiGeorge syndrome (4); histoplasmosis (4); myelofibrosis (4); rectal adenocarcinoma (4); respiratory infections (4); Wiskott-Aldrich syndrome (4); X-linked agammaglobulinemia (4); X-linked lymphoproliferative syndrome (4); anaplastic thyroid carcinoma (3); aphthous stomatitis (3); astrocytoma (3); atrophic gastritis (3); brain infarct (3); heart disease (3); hyperlipidemia (3); medulloblastoma (3); rectal cancer (3); T-cell acute lymphoblastic leukemia (3); X-linked hyper-IgM syndrome (3); adult onset immunodeficiency syndrome (2); Ataxia (2); autoinflammatory syndrome (2).
A further 195 diseases each share a sentence with STAT1 in 2 papers or fewer.